IGF2BP3 (insulin like growth factor 2 mRNA binding protein 3)
Diseases named in the same sentence as IGF2BP3 in open-access papers (continued):
Sharing a sentence is not in itself a finding about the gene and the disease.
glioma (continued). "However, how IGF2BP3 induces this immunosuppressive polarization remains largely unknown, and further studies will help to elucidate the effects of IGF2BP3 on GBM cells and its immune microenvironment, thereby providing a basis for the diagnosis and treatment of glioma." (PMID 35031058, 2022).
gastric cancer (64 papers, 2017 to 2026). A primary or metastatic malignant neoplasm involving the stomach. "Clinicopathological analysis reveals significant associations between IGF2BP3 expression and cancer stages in gastric cancer, and with cancer grades in liver cancer." (PMID 40765570, 2025). "Elevated IGF2BP3 levels were significantly associated with advanced tumor stages in gastric cancer and higher tumor grades in colorectal cancer, indicating its involvement in tumor progression and differentiation." (PMID 40765570, 2025). "For example, in the microenvironment of gastric cancer, cancer-associated fibroblasts modulate the immune response of tumor cells and promote a malignant phenotype by regulating IGF2BP3 expression." (PMID 40088376, 2025). "IGF2BP3 has been associated with gastric cancer progression, with high expression in four gastric cancer subtypes indicating its potential role in promoting cell growth and invasion." (PMID 38665783, 2024). "In gastric cancer, IGF2BP3 is upregulated and positively associated with lymphoid metastasis, high Ki-67 expression and poor outcome." (PMID 35986300, 2022). "As a member of the IGF2BPs family, a series of studies have shown that IGF2BP3 is associated with the proliferation and metastasis of colon cancer, bladder cancer, gastric cancer, and other malignant tumours." (PMID 35980273, 2022). "The analysis revealed the presence of IGF2BP3-related genes across three types of gastrointestinal cancers, excluding gastric cancer, indicating that mutations in IGF2BP3 could be crucial in the initiation and progression of these cancers." (PMID 40765570, 2025). "High expression of IGF2BP3 is associated with low survival rate of patients with gastric cancer (GC)." (PMID 35047058, 2022). "The expression of IGF2BP3 increased with the progression of gastric cancer, while the expression of NEDD4L increased only in the early stage." (PMID 41561975, 2025). "Reader IGF2BP3 is highly expressed in stomach cancer tissues and hypoxia-treated stomach cancer cells alongside HIF-1α." (PMID 40102715, 2025). "In gastric cancer cells that are exposed to hypoxia, deletion of IGF2BP3 suppresses VEGF expression." (PMID 38053093, 2023). "In summary, IGF2BP3 is also a tumor-promoting factor of gastric cancer, participates in the progression of gastric cancer through multiple pathways, and is expected to be a target for inhibiting the progression of gastric cancer." (PMID 37298373, 2023). "For instance, circ-TNPO3 functions as a protein decoy for the insulin-like growth factor 2 mRNA binding protein 3 (IGF2BP3) to inhibit the capacity of gastric cancer cells to proliferate." (PMID 38003674, 2023). "miR-34a inhibits proliferation and invasion and induces apoptosis through the miR-34a/IGF2BP3 axis in gastric cancer cells." (PMID 37298373, 2023). "In gastric cancer, IGF2BP3 physically binds and stabilizes PKMYT1 mRNA in an m6A-dependent manner, facilitating cell invasion and migration." (PMID 37280679, 2023). "Another different mechanism of angiogenesis in gastric cancer has been revealed: the disruption of IGF2BP3 weakens the stability of m6A-enriched HIF1A, consequently inhibiting hypoxia-induced cell migration and angiogenesis." (PMID 37280679, 2023). "As previously discussed, HDGF expression is fostered via the METTL3/IGF2BP3-HDGF mRNA axis in an m6A-dependent manner in gastric cancer." (PMID 37280679, 2023). "For instance, circ-TNPO3 inhibits gastric cancer (GC) metastasis by decoying insulin-like growth factor 2 binding protein 3 (IGF2BP3) protein." (PMID 36380816, 2023). "In gastric cancer, IGF2BP3 directly recognizes and binds to the m6A site on HDGF mRNA and enhances its stability." (PMID 37298373, 2023). "For example, IGF2BP3 promoted the proliferation ability by regulating the expression of MYC through mRNA stabilisation in gastric cancer." (PMID 37743642, 2023).
gastric cancer (continued). "In gastric cancer, IGF2BP3, an m6A reader, positively regulates HIF-1α gene and promotes angiogenesis through m6A regulation and can also regulate the VEGF gene to facilitate angiogenesis in colon cancer." (PMID 36246403, 2022). "For example, ALKBH5 serves as a suppressor for the metastasis of gastric cancer by downregulating the expression of protein kinase and membrane-associated tyrosine/threonine 1 (PKMYT1) in an IGF2BP3-m6A-mediated manner." (PMID 35804965, 2022). "In stomach cancer, m6A reader IGF2BP3 regulates the hypoxia-induced metastasis by increasing the expression of HIF-1α in an m6A-dependent manner." (PMID 35804965, 2022). "In gastric cancer, miR-34a directly targets IGF2BP3, overexpression of IGF2BP3 promotes cell proliferation and invasion." (PMID 33015074, 2020). "Previous studies revealed that IGF2BP3 promoted tumor proliferation and progression in colorectal cancer, gastric cancer, and glioblastoma." (PMID 33240891, 2020). "The overexpression of IGF2BP3 was related to poor disease-specific survival of gastric cancer, regulated by miRNA-34a." (PMID 32710725, 2020). "According to previous studies, IGF2BP3 is highly expressed in numerous cancer tissues, such as esophageal cancer, lung cancer, prostate cancer, gastric cancer, and colorectal malignancies." (PMID 32984260, 2020). "IGF2BP3 (Insulin-like growth factor-2 mRNA-binding protein 3) overexpression has been reported to be correlated with poorer survival in gastric cancer patients." (PMID 29036883, 2017). "IGF2BP3 interacts with m6A sites on mRNA, enhancing mRNA stability and supporting tumor angiogenesis and glycolysis, thus aiding the growth and liver metastasis of gastric cancer." (PMID 39791162, 2025). "Moreover, circRNAs such as circ-transportin 3 (TNPO3) and circular nuclear factor of activated T cells 3 (circNFATC3) interacted with IGF2BP3 protein and further regulated its expression in gastric cancer." (PMID 39856555, 2025). "Additionally, in gastric cancer, IGF2BP3 directly recognizes the m6A site on HDGF (Heparin Binding Growth Factor) mRNA, a process initiated by METTL3." (PMID 38902779, 2024). "Thus, IGF2BP3 can be targeted in gastric cancer and CRC cells to control tumor growth by inhibiting angiogenesis, achieving clinical treatment objectives." (PMID 39295872, 2024). "Insulin like growth factor II mRNA binding protein 3 (IGF2BP3) is an RNA binding protein with multiple roles in regulation of gene expression at the post-transcriptional level and is implicated in tumorigenesis and progression of numerous cancers including gastric cancer (GC)." (PMID 37340423, 2023). "The expression of MYC proto-oncogene, as well as bHLH transcription factor (MYC) and its target, snail family transcriptional repressor 1 (SNAI1), is inhibited when circ-TNPO3 sequesters IGF2BP3, which reduces the ability of gastric cancer cells to proliferate and metastasize." (PMID 38003674, 2023). "In gastric cancer, higher expression of METTL3 is associated with poor prognosis, and mechanistically, METTL3 mediates the m6A modification of HDGF mRNA in a manner with IGF2BP3-dependent HDGF mRNA stability." (PMID 35541906, 2022). "miR-125a-5p targeted IGF2BP3 in advanced gastric cancer to inhibit the cancer ́s progression." (PMID 36401176, 2022). "Furthermore, a tight correlation between IGF2BP3 expression and lymph node metastasis is found in colorectal adenocarcinoma, oral squamous cell carcinoma, and gastric cancer." (PMID 34329193, 2021). "Finally, IGF2BP3 plays significant biological roles in thyroid cancer 37, breast cancer 38, gastric cancer 39, and colorectal cancer." (PMID 33033522, 2020). "This study aims to investigate the biological function and clinical significance of IGF2BP3 in gastric cancer (GC)." (PMID 38448411, 2024). "For instance, elevated levels of YTHDF1 and YTHDC2 are adverse prognostic factors for gastric cancer (GC), while increased IGF2BP3 levels are adverse prognostic factors for bladder cancer." (PMID 39062595, 2024).
gastric cancer (continued). "Knockdown of IGF2BP3 inhibits hypoxia-induced cell migration and angiogenesis by modulating HIF-1α in stomach cancer." (PMID 40102715, 2025). "IGF2BP3, acting as an m6A reader, recognized an m6A modification on PKMYT1 mRNA, enhancing its stability and promoting the invasion and migration of gastric cancer cells." (PMID 39791162, 2025). "initially identified circRNAs that bind to IGF2BP3 in gastric cancer (GC) cells." (PMID 41169378, 2025). "CircARID1A acted as a scaffold to promote the interplay of IGF2BP3 and SLC7A5 mRNA, which ultimately increased the stability of SLC7A5 mRNA and thus promoted gastric cancer cell proliferation." (PMID 38577615, 2024). "Targeting IGF2BP3 in gastric cancer HGC-27 cells resulted in a significant downregulation of PKMYT1 expression, highlighting the potential role of the ALKBH5/PKMYT1/IGF2BP3 regulatory signaling pathway in gastric cancer metastasis." (PMID 38856795, 2024). "To validate the findings in human gastric cancer specimens, we first analyzed the expression levels of IGF2BP3 and MUC16 in 13 GLP and 30 gastric cancer tissues using immunohistochemistry." (PMID 36450891, 2023). "Circ-TNPO3 can act as a protein decoy for IGF2BP3, weakening the role of IGF2BP3 in stabilizing MYC mRNA, thereby inhibiting gastric cancer cell migration and proliferation." (PMID 37298373, 2023). "IGF2BP3 and MUC16 are overexpressed in gastric cancer cell lines, and they are significantly upregulated in diffuse gastric cancer cell lines and SRCC cell lines that are closely related to diffuse gastric cancer." (PMID 36450891, 2023). "Two genes were identified using immunohistochemistry (IHC), IGF2BP3 and MUC16, which specifically expressed in diffuse-type-related gastric cancer cell lines, and its knockdown inhibits PI3K-AKT pathway activity." (PMID 36450891, 2023). "For instance, the m6A reader IGF2BP3 recognizes and binds to the m6A site on HDGF mRNA, thereby enhancing the stability of HDGF mRNA in gastric cancer." (PMID 36257938, 2022). "In gastric cancer, METTL3 promoted the m6A modification of HDGF mRNA, and the m6A reader IGF2BP3 directly recognized and bound to the m6A site on HDGF mRNA and enhanced HDGF mRNA stability." (PMID 35144642, 2022). "For example, circ-TNPO3 can interact with IGF2BP3 to weaken the role of IGF2BP3 in stabilizing MYC mRNA, thereby regulating the MYC-SNAIL axis and inhibiting the proliferation and metastasis of gastric cancer (GC)." (PMID 36139074, 2022). "Similar studies in gastric cancer cells showed that METTL3 promotes m6A modification of the mRNA of recombinant protein hepatoma-derived growth factor (HDGF), whereas IGF2BP3 directly recognizes and binds to the m6A site on HDGF mRNA, enhancing its stability." (PMID 36064747, 2022). "IGF2BP3 is highly expressed in many tumors, including ESCC, lung adenocarcinoma, colon cancer, and gastric cancer, and leads to poor prognosis." (PMID 34054840, 2021). "To validate the findings of WTS in GLP tissues, we analyzed the expression of IGF2BP3 and MUC16 in the human gastric epithelial cell line GES1 and the human gastric cancer cell lines AGS (intestinal-type), NUGC4 (diffuse-type), and KATO III (signet ring cell carcinoma, SRCC)." (PMID 36450891, 2023). "In addition, circular RNA, circ-TNPO3 serves as a protein decoy to competitively interact with IGF2BP3, and the stabilization role of IGF2BP3 on c-MYC mRNA is weakened, leading to inhibition of metastasis in gastric cancer." (PMID 35541906, 2022). "Additionally, NSUN2-methylated lncRNA enhances the stability of glutaminase (GLS) mRNA by upregulating glutaminase expression through interaction with the IGF2BP3/HUR complex, thus facilitating reprogramming of glutamine metabolism and accelerating gastric cancer progression." (PMID 38902779, 2024).
gastric cancer (continued). "In addition, IGF2BP3 and METTL3 improve the expression of transcription factor HDGF by directly recognizing and binding the m6A-modified HDGF, which transcriptionally accelerates the expression of GLUT4 and ENO2 to facilitate glycolysis in gastric cancer." (PMID 37280679, 2023). "Previous study showed that IGF2BP3 could form a ternary complex of circFNDC3B-IGF2BP3-CD44 mRNA to increase CD44 expression in the translation process, finally promoting the migration and invasion of gastric cancer cells." (PMID 34986849, 2022). "In addition, upregulation of METTL3 in gastric cancer promotes tumor angiogenesis and glycolysis by promoting IGF2BP3-dependent hepatoma-derived growth factor (HDGF) mRNA stability, which is essential for increasing in glycolysis by activating GLUT4 and ENO2 in gastric cancer cells." (PMID 34616742, 2021). "Circ-hHBB3 binds HuR and degrades HuR, whereas Circ-TNPO3 competitively binds IGF2BP3 and inhibits the proliferation and metastasis of gastric cancer by regulating the MYC-SNAIL axis, which leads to malignant progression of GC." (PMID 35116058, 2021). "Investigators found that primary gastric cancer (GC) samples had a negative correlation between IGF2BP3 mRNA expression and miR-34a expression." (PMID 38725047, 2024).
breast carcinoma (62 papers, 2014 to 2025). "This study focused on exploring the diagnostic value of IGF2BP3 in breast cancer, particularly in TNBC." (PMID 40672753, 2025). "This study utilized immunohistochemistry (IHC) to assess the expression of the IGF2BP3 protein in 299 cases of breast cancer tissues, with the aim of investigating the clinical and diagnostic significance of IGF2BP3 in breast cancer." (PMID 40672753, 2025). "We suggest that IGF2BP3 is upregulated in breast cancer, especially in TNBC, and has potential diagnostic value for breast cancer and TNBC." (PMID 40672753, 2025). "IGF2BP3, an m6A‐binding protein, is upregulated in breast cancer and is intimately associated with tumor malignancy and prognosis." (PMID 39972939, 2025). "After evaluating the respective staining intensity scores, we found that, indeed, the PD-L1 expression in breast cancer was positively associated with the expression of METTL3 or IGF2BP3." (PMID 35197058, 2022). "In conclusion, our study has illustrated the critical role of METTL3-mediated m6A modification in PD-L1 mRNA stabilization in an IGF2BP3-associated manner in breast cancer cells." (PMID 35197058, 2022). "As a result, IGF2BP2 and IGF2BP3 showed significant prognostic values of being risk factors (HR > 1) for OS of breast cancer patients." (PMID 33585234, 2020). "The results of this study may provide valuable insights into the role of IGF2BP3 in breast cancer progression and its potential as a diagnostic and prognostic marker." (PMID 40672753, 2025). "Association of IGF2BP3 expression with clinicopathological parameters in breast cancer patients." (PMID 40672753, 2025). "The expression of IGF2BP3 is increased in many tumors, such as hepatocellular carcinoma, colorectal cancer, lung cancer, and breast cancer, and is associated with poor prognosis, indicating that IGF2BP3 may be a biomarker of malignant tumors." (PMID 37298373, 2023). "Extensive research has demonstrated the involvement of IGF2BP3 in various cancers such as breast cancer, colon cancer, and non-small cell lung cancer 45-47." (PMID 40083693, 2025). "For instance, IGF2BP3 overexpression has been documented to promote tumor invasiveness and predict adverse outcomes in breast carcinoma and lung adenocarcinoma." (PMID 40847370, 2025). "By comparing the mechanisms of IGF2BP3 in other tumors, such as IGF2BP3 targeting PD-L1 in breast cancer 2, our commentary highlights the unique role of the IGF2BP3/m6A/CDK6 axis in BCa." (PMID 40959282, 2025). "METTL3 also promotes PD-L1 mRNA stability via insulin-like growth factor 2 mRNA binding protein 3 (IGF2BP3), thereby impairing T cell-mediated cytotoxicity and reducing anti–PD-L1 therapy efficacy in breast cancer." (PMID 41247642, 2025). "METTL3 and IGF2BP3 augment the resistance of breast cancer cells to doxorubicin (Dox) through the regulation of m6A modification of HYOU1." (PMID 39972939, 2025). "Currently, some studies have reported on the expression and clinical significance of IGF2BP3 in breast cancer." (PMID 40672753, 2025). "Prior studies in hepatocellular and breast cancers show that IGF2BP3 (IMP3) binds the 3′ UTR of SREBP1c mRNA, stabilizing the transcript and enhancing SREBP1c nuclear accumulation and transactivation of lipogenic targets, including FASN." (PMID 41614778, 2025). "Conversely, in a study on breast cancer, IGF2BP3 expression levels were significantly upregulated in patients who responded well to immunotherapy." (PMID 40088376, 2025). "We further analyzed the value of IGF2BP3 in the differential diagnosis of breast cancer and normal breast tissue, as well as the differential diagnosis of TNBC and non-TNBC." (PMID 40672753, 2025). "Among 299 cases of breast cancer tissues, 34 were IGF2BP3 positive (11.4%, 34/299), while the IGF2BP3 positivity rate in 60 cases of normal breast tissues was 0.0% (0/60)." (PMID 40672753, 2025).